INSR (insulin receptor)
Diseases named in the same sentence as INSR in open-access papers (continued):
Sharing a sentence is not in itself a finding about the gene and the disease.
Insulin resistance (continued). "This DAF-2 variant aligned with both the INSR(A1135E) mutation found in a patient with Type A Insulin Resistance, and the compound heterozygous INSR(A1135V; N878S) mutation found in a patient with Rabson-Mendenhall Syndrome, a very severe form of insulin resistance." (PMID 27856697, 2017). "We have recently uncovered that the multifunctional RNA-binding protein Staufen1 is increased in DM1, and that it is capable of rescuing selected defects in DM1 cells, including alternative splicing of the INSR pre-mRNA, which is linked with insulin resistance." (PMID 26824521, 2016). "To define the cause-effect relationship between insulin resistance and mitochondrial dysfunction, we compared mitochondrial metabolism in induced pluripotent stem cells (iPSC) from 5 healthy individuals and 4 patients with genetic insulin resistance due to insulin receptor mutations." (PMID 26948272, 2016). "In summary, our findings establish that in humans, C-terminal SH2 domain mutations in PIK3R1 produce a metabolic phenocopy of insulin receptor dysfunction, with strikingly preserved liver fat, lipid profile, and plasma adiponectin despite severe insulin resistance." (PMID 27766312, 2016). "Similarly, deletion of the insulin receptor in mice to develop insulin resistance decreases cardiac contractility, which is associated with a reduction in ATP production and mitochondrial respiration." (PMID 27375480, 2016). "Loss of function of the insulin receptor (INSR) in humans produces severe insulin resistance." (PMID 26888756, 2016). "Considering that accumulated data showed a strong association between INSR and insulin resistance, allelic polymorphism of INSR may impose a genetic predisposition for the development of PCOS." (PMID 25622255, 2015). "Therefore, an elevated serum level of insulin can theoretically cause breast cancer via the crosstalk between insulin and insulin receptor and/or insulin-like growth factor receptors, especially in the presence of insulin resistance." (PMID 26171401, 2015). "Also, the INSR PmlI "pp" genotype appeared to confer a decreased risk for serum insulin levels and insulin resistance in the controls." (PMID 27141540, 2015). "For instance, mice with conditional null mutation of the insulin receptor in liver exhibit impairment of insulin clearance and hepatic insulin resistance with elevated lipogenesis, and a rise in plasma ApoB100/ApoB48 levels in parallel to low plasma triacylglycerol levels and obesity." (PMID 26284027, 2015). "Finally, it has been demonstrated that liver-specific ablation of CerS2 in mice causes hepatic insulin resistance due to reduced phosphorylation of the insulin receptor and its inability to translocate into detergent-resistant membranes." (PMID 25993337, 2015). "Moreover, in a long-term follow-up (up to 30 years) report of 11 patients with INSR mutations (8 with type A insulin resistance and 3 with RMS), nephropathy occurred in 5, including 1 of the RMS patients who had proteinuria of up to 600 mg/day." (PMID 25358339, 2014). "PKCε is the isoform most often implicated in association with hepatic insulin resistance, PKCε in liver may affect its ability to phosphorylate the substrates or InsR trafficking in hepatocytes." (PMID 25160038, 2014). "INSR mis-splicing has been linked to the insulin resistance phenotype in DM patients." (PMID 24179176, 2014). "Zinc, however, is known to increase insulin receptor phosphorylation and downstream protein phosphorylation in insulin signaling pathways, such that a decrease in body zinc status might cause insulin resistance." (PMID 25153887, 2014). "For example, excess of GH leads to reduced insulin receptor levels in liver, which may be associated with GH-induced hepatic insulin resistance." (PMID 23840818, 2013).
Insulin resistance (continued). "Both humans with insulin resistance caused by inherited mutations in the insulin receptor and mice with a liver-specific deletion of the insulin receptor exhibit hyperglycaemia and hyperinsulinemia, but both are protected against hepatic steatosis and hypertriglyceridemia." (PMID 24284392, 2013). "Adiponectin, SHBG- and IGFBP1 are all commonly reduced in people with obesity-related insulin resistance and various lipodystrophies, so these markers are helpful diagnostically in distinguishing those with insulin receptor dysfunction from those with other causes of severe insulin resistance." (PMID 23766565, 2013). "Patients with INSR mutation differ biochemically from patients with more common insulin resistance associated with the metabolic syndrome by having high levels of adiponectin, sex-hormone-binding globulin (SHBG), and insulin-like growth factor-binding protein 1 (IGFBP1)." (PMID 23766565, 2013). "Interestingly, insulin resistance in the podocyte alone is adequate to achieve signs of DN, as demonstrated in a knock out mouse model of insulin receptor deficiency under normoglycemia." (PMID 22615747, 2012). "Also, rare clinical syndromes due to mutations in the INSR gene have been identified in patients with monogenic forms of severe insulin resistance." (PMID 22701472, 2012). "Furthermore, in knockout mice expressing a brain-restricted insulin receptor deficiency (NIRKO) brain insulin resistance impairs insulin-mediated activation of either the PI3K/Akt/GSK-3β or MAPK/ERK pathways in cerebellar granule cells." (PMID 22383997, 2012). "We have hypothesized that dysfunction of membrane of myocytes could alter the insulin receptor function, and as a result an increase may occur in the risk for developing insulin resistance." (PMID 22701119, 2012). "Inflammation causes insulin resistance via inhibiting the signaling downstream of insulin receptor." (PMID 22363882, 2011). "Interestingly,it was demonstrated that serine phosphorylation of theβ-chain of the insulin receptor causes insulin resistance invitro." (PMID 17389770, 2007). "Indeed, insulin receptor signalling deregulation seems to play a crucial role in causing atherosclerosis related to insulin-resistance." (PMID 17971205, 2007). "Several studies were conducted to identify whether the mutationsof INSR could explain insulin resistance in women withPCOS." (PMID 17389770, 2007). "Interestingly, TNF-α seems to be responsible for the insulin-resistance associated with obesity, since decreases the tyrosine kinase activity of the insulin receptor." (PMID 17971205, 2007). "Furthermore, mutations in the insulin receptor can impair insulin signaling, leading to reduced glucose uptake and compensatory hyperinsulinemia, which ultimately contributes to the development of insulin resistance." (PMID 40868096, 2025). "Moreover, from another inference result, the drugs lopinavir and ritonavir might cause insulin resistance in COVID-19 via negative regulation of the insulin receptor pathway during ER stress." (PMID 38778394, 2024). "Additionally, activation of the NF-κB signaling pathway increases the levels of protein phosphatase 1B (PTP1B), which dephosphorylates the insulin receptor or its substrate, hindering the insulin receptor's ability to bind with insulin, and causing insulin resistance." (PMID 37485384, 2023). "Second, elevated HCY could either impair insulin secretion through alterations in beta-cell glucose metabolism and generation of key stimulus-secretion coupling factors, or induce insulin resistance and cause diabetic phenotypes by protein cysteine-homocysteinylation of the pro-insulin receptor." (PMID 37322514, 2023). "Thus, the abnormal splicing of the chloride channel (CLCN1) is associated with myotonia, that of the insulin receptor (INSR) with insulin resistance, that of the calcium channel (Cav1.1) with muscle weakness, and that of the sodium channel (SCN5A) with arrhythmias." (PMID 36902726, 2023).
Insulin resistance (continued). "Insulin receptor activity (tyrosine kinase) also decreases simultaneously, leading to structural or functional defects in various enzymes in the glucose metabolic pathway (e.g., glucokinase) and impaired glucose metabolism in the body, which results in insulin resistance and IGF-1 deficiency." (PMID 36120463, 2022). "Prior work has demonstrated that decreased IRS1 expression, the gene encoding the insulin receptor substrate, causes insulin resistance—our work further suggests that impaired expansion of the gluteofemoral and abdominal subcutaneous fat depots may be involved in this physiological insult." (PMID 35773277, 2022). "Furthermore, viral infections may cause insulin resistance because of the downregulation of insulin receptor expression in skeletal muscle due to virus‐induced interferon gamma." (PMID 35478440, 2022). "Jerrold Olefsky showed that insulin resistance could be explained by both defects in the insulin receptor and postreceptor defects, and Takashi Kadowaki in Simeon Taylor’s group identified insulin receptor mutant alleles in a patient with severe insulin resistance." (PMID 34717951, 2021). "In cancer patients with insulin resistance, the elevated levels of circulating insulin accompanied frequently by insulin receptor (IR) overexpression in cancer cells may be associated with atypical stimulation of non-metabolic effects of IR, including cell proliferation, migration, and survival." (PMID 33008076, 2020). "Moreover, the epigenetic induction of PDGFA, which encodes platelet-derived growth factor α (PDGF-AA), appears to be central to hepatic disease progression, as PDGF-AA causes insulin resistance by reducing hepatic insulin receptor density in a protein kinase C (PKC)-dependent manner." (PMID 33193730, 2020). "We aimed to determine whether insulin resistance mediates in part the association between race and breast cancer prognosis, and if insulin receptor (IR) and insulin-like growth factor receptor (IGF-1R) expression differs between tumors from Black and White women." (PMID 32393319, 2020). "Metabolically, the deletion of insulin receptor in osteoblasts as represented in the Ob-IR-/- model, results in marked increased in peripheral adiposity accompanied by glucose intolerance, hyperglycemia, hypoinsulinemia, and target tissue insulin resistance caused by reduced undercarboxylated OCN." (PMID 33537005, 2020). "Insulin resistance is associated with peripheral resistance of glucose uptake at the skeletal muscle site and manifests as impaired insulin signaling through the phosphorylation of insulin receptor substrate-1, which inhibits tyrosine kinase activity at the insulin receptor." (PMID 33076282, 2020). "Six patients with high insulin resistance and acanthosis nigricans were classified into two types: A and B. Type A is a disease caused by congenital genetic anomalies of the insulin receptor; and type B is an acquired disease caused by the insulin receptor antibody." (PMID 32337291, 2020). "The expression of insulin receptor and insulin induced uptake of glucose is stimulated by vitamin D; these studies are supported by the facts that vitamin D receptors are present on the beta cells and skeletal muscles, and vitamin D deficiency can cause insulin resistance and type 2 diabetes." (PMID 29320437, 2018). "Thus, it has been suggested that insulin resistance may be caused in part by the disruption of caveolae/lipid rafts that leads to altered localization of insulin receptor and disassembly of insulin signaling molecules." (PMID 28030645, 2016). "Such a condition can be sufficient to trigger insulin resistance, as mice with heterozygous loss of protein targeting to glycogen, a scaffold protein involved in glycogen synthesis, show significant reduction in liver glycogen and an attenuated insulin receptor signalling." (PMID 26100075, 2015).
Insulin resistance (continued). "Insulin receptor gene (INSR) mutations are very rare but at least more than 30 INSR mutations have been shown to mediate insulin receptor dysfunction, and these mutations may induce insulin resistance with polygenic defects in its downstream signaling." (PMID 23781214, 2013). "Consistent with these latter findings, we have shown that defects in HMGA1 expression and/or function, by negatively affecting insulin receptor (INSR) signaling in insulin target tissues, may cause insulin resistance and increase susceptibility to type 2 diabetes mellitus." (PMID 24367622, 2013). "The “Insulin Receptor Signaling” pathway as well as the “Metabolic Disease” and “Endocrine System Disorders” functions suggest the involvement of the relevant miRNA/mRNA couples in insulin resistance, a classic DM clinical feature, predisposing to Type 2 diabetes." (PMID 22768114, 2012). "Iron overload leads to the formation of ROS, resulting in insulin resistance through the downregulation of insulin receptor expression and worsening of glucose and lipid metabolism disorders." (PMID 41596552, 2026). "While genetic predisposition has a substantial influence on the risk of developing MetS, other intrinsic factors, including chronic inflammation, insulin resistance (InsR), and altered neurohormonal activation, also play crucial roles." (PMID 42072656, 2026). "In individuals with chromium deficiency, supplementation with chromium picolinate has been shown in clinical trials to enhance insulin receptor activation, improve glucose tolerance, and reduce insulin resistance." (PMID 41170369, 2025). "Both adipose tissue inflammation and lipid metabolism dysregulation contribute to insulin receptor impairment, disrupted insulin signaling pathways, and subsequent development of insulin resistance and T2DM." (PMID 40078991, 2025). "These inflammatory kinases promote insulin resistance by negatively regulating key components of the insulin signaling cascade, such as the insulin receptor and insulin receptor substrate (IRS)." (PMID 40004236, 2025). "TRIM32 ubiquitylates INSR and facilitates its proteasomal degradation, leading to severe insulin resistance and fat accumulation within the liver of high-fat diet induced obese (DIO) mice." (PMID 39747658, 2025). "We report the case of a 3-month-old Honduran girl with a homozygous exon 14 deletion in INSR who presented with severe insulin resistance, metabolic dysregulation, and dysmorphic facial features." (PMID 41025026, 2025). "In cultured cells and animal tissues, SOCS1/3 promote insulin resistance by facilitating the ubiquitination and degradation of insulin receptor substrates (IRS1/2)." (PMID 40918255, 2025). "Hypomagnesemia alters the activity of pancreatic β-cells and modifies insulin secretion, while also promoting insulin resistance through the modulation of insulin receptor autophosphorylation." (PMID 40650304, 2025). "These inflammatory processes activate signaling pathways, including serine kinases, IKKβ, and JNK1, which inhibit insulin receptor signaling and enhance insulin resistance." (PMID 40149843, 2025). "The same cytokines induce insulin resistance systemically by inhibiting insulin receptor signalling in the liver and skeletal muscle via SOCS3." (PMID 41010046, 2025). "In T2DM, characterized by hyperinsulinemia, insulin resistance in the brain can arise from reduced insulin receptor expression and receptor-activating enzymes." (PMID 39935840, 2025). "ER stress activates inflammatory signaling (e.g., JNK, IRE1), impairs insulin receptor signaling, and contributes to peripheral and hypothalamic insulin resistance." (PMID 41567335, 2025). "On a genetic level, the INSR and FBN3 genes have been identified as key contributors to insulin resistance in PCOS, encoding proteins involved in insulin receptor function and extracellular matrix formation, respectively." (PMID 40149685, 2025).
Insulin resistance (continued). "Factors influencing insulin resistance include elevated free fatty acids due to lipolysis and insufficient coupling between insulin receptor (IR) activation and GLUT4 receptor translocation to the cell surface." (PMID 40724491, 2025). "In contrast, progesterone promotes insulin resistance, possibly through interference with insulin receptor signaling and impaired GLUT4 translocation, necessitating greater insulin secretion from β-cells to maintain glucose homeostasis." (PMID 40076938, 2025). "Decreased INSR levels ultimately led to cell dysfunction and insulin resistance, whereas NP-NAR’s elevated INSR levels in the liver improved HFD-induced IR." (PMID 40038718, 2025). "Hepatic insulin resistance, a hallmark pathogenic feature of T2DM, is caused by decreased hepatocellular insulin receptor substrate." (PMID 39803222, 2025). "Reduced expression of insulin signalling pathway genes in patients with insulin resistance (INSR, AKT, PIK3R1, IRS2) indicates a diminished insulin response in both VAT and SAT." (PMID 40806527, 2025). "In hepatocytes, excessive FFAs activate PKCε, which inhibits insulin receptor phosphorylation, worsening insulin resistance and mitochondrial dysfunction." (PMID 41235339, 2025). "These include defects in insulin receptor tyrosine phosphorylation, which reduces downstream signaling and promotes insulin resistance." (PMID 40149685, 2025). "Insulin resistance is characterized by a deteriorated physiological response of peripheral tissues to the metabolic effects of insulin; and occurs due to a decrease in insulin receptor expression in tissues that play a role in energy homeostasis." (PMID 39879508, 2025). "This involves direct impediment of insulin receptor and insulin receptor substrates-1,2 activation and degradation, which are pivotal in the pathogenesis of insulin resistance." (PMID 40519917, 2025). "It has been shown that homocysteine induces insulin resistance and contributes to the diabetic phenotype through protein cysteine–homocysteinylation of the pre-insulin receptor." (PMID 40732347, 2025). "In conclusion, our results demonstrate that TRIM32 promotes diet-induced hepatic insulin resistance by targeting the INSR to degradation." (PMID 39747658, 2025). "Many of these genes, including APOB, INSR, and PPARG, have multiple sources of supporting evidence and are implicated in known MASLD mechanisms like lipid metabolism, insulin resistance, and adiposity." (PMID 40065360, 2025). "Meanwhile, in HUBC mice, we noted that BACE1 overexpression led to a decreased InsR level, whose downstream pathway is important in glucose homeostasis and insulin resistance." (PMID 40507910, 2025). "Impairment of Mg homeostasis at insulin receptor will lead to insulin resistance and decrease of insulin secretion in β cells, leading to an increase in GDM risk." (PMID 40612310, 2025). "Studies have shown that TNF-α can activate pathways (like sphingolipid and NF-κB signaling) that impair insulin receptor autophosphorylation and promote insulin resistance in both adipocytes and skeletal muscle." (PMID 40722699, 2025). "The altered expression of insulin receptor substrate genes (IRS1/2) suggests the potential development of hepatic insulin resistance, indicating an imbalance in glucose and lipid metabolism following PFOS exposure." (PMID 40003090, 2025). "In obesity and diabetes, dysregulated post translational modification networks disrupt insulin receptor signaling, disturb organelle quality control, and impair beta cell function, which promotes insulin resistance and beta cell failure." (PMID 41373704, 2025). "Previous studies have indicated that impairments in INSR expression or functionality can lead to insulin resistance and DM." (PMID 41141349, 2025). "This indicates that HFD-induced systemic insulin resistance and liver-specific INSR downregulation were sufficient to developing impaired glycemia and fatty liver phenotype in HFD-fed DIO mice." (PMID 39747658, 2025).